BTLA (B and T lymphocyte associated)
Diseases named in the same sentence as BTLA in open-access papers (continued):
Sharing a sentence is not in itself a finding about the gene and the disease.
infection (34 papers, 2010 to 2025). The state of being infected such as from the introduction of a foreign agent such as serum, vaccine, antigenic substance or organism. "BTLA could be a potential therapeutic target/risk marker for patients susceptible to developing subsequent secondary infections." (PMID 25673430, 2014). "Analysis of infectious virus produced in the ovaries revealed significant differences in the time course of primary clearance in WT versus HVEM- and BTLA-deficient mice after low dose infection correlating with the absolute numbers of virus specific CD8 T cells." (PMID 24205056, 2013). "In addition, BTLA-deficient mice have exhibited enhanced pathogen clearance compared to wild-type (WT) mice in the early phase of infection, while agonistic anti-BTLA antibodies have been shown to rescue mice from lipopolysaccharide (LPS)-induced endotoxic shock." (PMID 38418488, 2024). "However, whether BTLA can induce T-cell immune exhaustion and increase the risk of infection remains unclear." (PMID 38418488, 2024). "Moreover, little is known regarding the mechanisms underlying BTLA expansion in patients with HBV-ACLF, and whether BTLA-deficient or agonistic anti-BTLA antibodies can rescue T-cell immune exhaustion and reduce the risk of infection remains to be investigated." (PMID 38418488, 2024). "Given their similar risk profiles for secondary infections, this unifying trend of CD3+ lymphocyte HVEM+BTLA+ co-expression suggests a promising immune modulation target warranting further exploration." (PMID 37305124, 2023). "Since BTLA is widely expressed on the surface of immune cells, its relation to immune response of infection including innate immune and adaptive immune has been a hot topic." (PMID 34163466, 2021). "BTLA expression increases in various infectious diseases, which is generally related to an impaired immune response against infection." (PMID 33859648, 2021). "Since BTLA can provide both inhibitory and pro-survival signals to T cells, it plays a dual role during infection." (PMID 33859648, 2021). "This function of BTLA as a trans-activating ligand delivering pro-survival signals through HVEM expressed on T cells has also been proposed for HVEM during infection with the intracellular bacteria Listeria monocytogenes." (PMID 33665363, 2021). "Stimulated by the Listeria, innate immune cells of BTLA deficient mice secreted significantly more proinflammatory factors, which indicated that BTLA played an important regulatory role in early host innate immune response against infection." (PMID 34163466, 2021). "Treating septic mice with anti-BTLA antibody, cytokines and inflammatory cells increased in the original site of infection, and the mice exhibited more severe organ impairment and lower survival rate." (PMID 34163466, 2021). "To determine if the differences in ocular disease pathogenesis were a result of differences in viral replication early in infection, we measured viral titers in the tear film at 1, 3, and 5 dpi in BTLA−/− LIGHT−/−, CD160−/− LIGHT−/−, and CD160−/− BTLA−/− mice." (PMID 32398314, 2020). "In 2015, the BTLA-HVEM signaling pathway was reported to help intestinal parasites (especially Strongyloides stercoralis) maintain an infection." (PMID 30984188, 2019). "Upregulation of BTLA on CD8α+ DC was further confirmed by flow cytometry analysis of cells after vitro and in vivo infection with VACV-WR." (PMID 24205056, 2013). "We further characterized OT1 cell-accumulation by measuring the number of OVA-specific cells in different sites from WT and BTLA knockout mice after infection." (PMID 24205057, 2013). "BALB/c mice were injected intraperitoneally with recombinant plasmid DNA encoding BTLA (pBTLA), pcDNA3.1, or PBS on 0 and 7 days before infection and 7 days postinfection." (PMID 21042564, 2010).
infection (continued). "Our findings demonstrate that infection of BALB/c mice with HSV-1 KOS strain by corneal scarification resulted in upregulation of BTLA expression in the infected corneas and in CD4+ T cells from murine peripheral blood." (PMID 21042564, 2010). "While at the anti-inflammatory stage, high expression of BTLA inhibits the activation of immune cells, and excessive immune suppression may lead to a secondary infection and bad prognosis." (PMID 34163466, 2021). "On the contrary, some studies found that the expression of BTLA help fight against infection." (PMID 34163466, 2021). "Additionally, deficiency of either BTLA or HVEM leads to decreased amounts of adult parasites in the small intestine, while reducing the larval output in the process of infection." (PMID 33859648, 2021). "Future studies are also necessary to determine whether modulation of BTLA/HVEM co-signaling can fine tune the immune response to Mtb to promote durable control of infection and prevent progression to TB disease." (PMID 31497018, 2019). "Furthermore, a higher frequency of CD4+BTLA+ cells was found in SIRS patients who subsequently developed infection." (PMID 25673430, 2014). "Between day 4 and day 6 post-infection, BTLA surface expression was induced on 20–25% of B8R-, A8R-, and B2R-tetramer positive cells, decreased by day 15, and was nearly undetectable by day 64 after infection." (PMID 24205056, 2013). "However, one must note that nearly all of the CD4+ T cells expressed BTLA in the majority of septic patients who developed a secondary infection." (PMID 24289156, 2013). "Furthermore, it has been shown that non-septic critically ill patients with greater than 80% BTLA expression on CD4+ T lymphocytes were at increased risk of developing secondary infection." (PMID 37305124, 2023). "Moreover, BTLA-/- mice have also shown resistance to infection in several other disease models." (PMID 33859648, 2021). "• An increased percentage of BTLA+CD4+ T cells in critically ill patients associated with poor outcomes and a longer hospital length of stay; thus, future studies are warranted examining BTLA expression on CD4+ T cells as a potential biomarker for subsequent infections and poor septic outcomes." (PMID 24289156, 2013). "Specifically, ECs demonstrated significantly low-level BTLA expression in CD4+ T cells (21, 49, 84, and 133 days post-infection), as well as diminished TIGIT expression in CD8+ T cells (49, 84, and 133 days post-infection) compared to PGs." (PMID 40637373, 2025). "Specifically, we observed lower BTLA expression on resting CD4+ T cells during both acute and chronic infection phases in ECs (49, 84, and 133 days post-infection) while maintaining comparable IC expression levels on resting CD4+ TCM relative to PGs." (PMID 40637373, 2025). "Here, we aim to analyze BTLA expression in patients with HBV-ACLF and evaluate its relationship with disease severity, prognosis, and infection complications." (PMID 38418488, 2024). "Quantitative RT-PCR showed that the relative expression levels of immune checkpoint CTLA-4, LAIR-1, GITR, BTLA, TIM-3, or PD-1 mRNA in the lung presented decreased levels on day 3 or 7 after infection in KI or KO mice." (PMID 36275680, 2022). "In conclusion, we have found evidence of increased soluble BTLA and TIM-3 as well as CD27 in the immunosuppressed pediatric burn patients who go on to develop infections." (PMID 35958579, 2022). "During infection with murine hepatitis virus strain-3 (MHV-3), BTLA-/- mice show markedly improved spleen and liver injuries and reduced mortality." (PMID 33859648, 2021). "During infection with primary cytomegalovirus (CMV), BTLA is highly induced in CD8+ T cells, and BTLA blockade enhances CMV-specific CD8+ T cell proliferation." (PMID 33859648, 2021). "Three days after infection with Ad.EGFP, Ad.CCR7, Ad.BTLA, or Ad.CCR7 + BTLA, the cellular morphology of imDCs was examined under SEM." (PMID 28393074, 2017).
infection (continued). "In vitro chemotaxis experiments were performed with cells 3 days after infection to determine the respective effects of CCR7 and BTLA overexpression on imDC migration." (PMID 28393074, 2017). "Natural host ligands (i.e. BTLA and LTα) of the herpes simplex virus entry receptor, HVEM, can inhibit binding of the virus glycoprotein gD to HVEM and suppress infection." (PMID 27783670, 2016). "Our data indicate that both BTLA and HVEM are required for the accumulation of antigen-specific T cells during LM-OVA infection." (PMID 24205057, 2013). "Imperfect control of lymphocyte activity, due to SNPs of PTPN22, CTLA-4, BTLA, and some other elements of the immune response, makes it difficult to stop immune activity that is no longer needed after recovery from infection." (PMID 38792338, 2024). "Here, we report that BTLA levels are significantly increased in the circulating and intrahepatic CD4+ T cells from patients with HBV-ACLF, and are positively correlated with disease severity, prognosis, and infection complications." (PMID 38418488, 2024). "Unfortunately, both soluble TIM-3 and BTLA have received less attention as immune checkpoints during injury that results in infections with no human studies exploring their role in burn injury." (PMID 35958579, 2022). "Thus, soluble BTLA and TIM-3 as well as CD27 represent intriguing proteins for further research in burn injury as these proteins may be playing a key role in augmenting an appropriate immune cell response, leaving these individuals highly susceptible to infections." (PMID 35958579, 2022). "Soluble BTLA and TIM-3 were significantly increased for those who developed an infection after thermal injury from those that did not (BTLA: 3998 pg/mL vs 1142 pg/mL; TIM-3: 3225 pg/mL vs 752.1 pg/mL)." (PMID 35958579, 2022). "While there is still limited research on soluble CD27, BTLA, and TIM-3, these markers represent highly important indicators (optimal threshold >1129 pg/mL, >1353 pg/mL, and >705.3 pg/mL, respectively) for the development of infection in pediatric burn injury." (PMID 35958579, 2022). "The reductions in infiltrating leukocytes in the BTLA−/− LIGHT−/− and CD160−/− LIGHT−/− mice indicate that multiple HVEM binding partners play roles in promoting leukocyte infiltration in the cornea following infection." (PMID 32398314, 2020). "To further investigate the requirement of BTLA during CD8+ T cell differentiation in response to LM-OVA infection, we performed competitive adoptive co-transfers with equal numbers of WT (CD45.1+CD45.2+) and Btla−/− (CD45.2+) OT1 cells transferred into CD45.1+ hosts." (PMID 24205057, 2013). "BTLA expression increased in CD4+ T cells, peaking on day 10 after infection." (PMID 21042564, 2010). "Notably, ECs exhibited significantly lower BTLA expression in activated CD4+ T cells (49 and 133 days post-infection) and TIGIT expression in activated CD8+ T cells (49, 84, and 133 days post-infection)." (PMID 40637373, 2025). "Treg and BTLA+ T cells expand during infection and either Treg depletion or absence of BTLA or its ligand, Herpes Virus Entry Mediator (HVEM), results in elevated IL-9 production, accelerated mast cell activation and rapid expulsion of S. ratti from the intestine." (PMID 33351862, 2020). "Given that infection with HIV has been shown to lead to modulation of T cell phenotypic profiles, we next determined the effect of HIV infection on the total CD4 T cell expression profiles of BTLA, CTLA-4, and PD-1 in individuals with LTBI and with active TB, using a Boolean gating strategy." (PMID 31497018, 2019). "Prior studies in BTLA-deficient mice show increased differentiation of naïve CD8+ T cells into central memory cells in the absence of BTLA, suggesting that our results could be explained by interference of HVEM-BTLA signaling by gD during acute infection." (PMID 22666282, 2012).
hematological malignancies (8 papers, 2016 to 2024). "Dysregulation of the BTLA/HVEM axis has been described in a plethora of solid tumors as well as in hematological malignancies." (PMID 38233898, 2024). "BTLA/HVEM dysregulation is commonly found and linked to poor prognosis in solid and hematological malignancies." (PMID 37649037, 2023). "Notoriously, the prognostic value of BTLA expression has already been reported in other hematological malignancies." (PMID 37041226, 2023). "Further, aberrant surface expression and levels of soluble BTLA (sBTLA) in sera have been related to prognosis in various solid tumors and hematological malignancies." (PMID 33917094, 2021). "The usefulness of BTLA blockade is also assessed in the treatment of hematological malignancies." (PMID 38233898, 2024). "In hematological malignancies, BTLA/HVEM axis dysregulation decreased perforin and granzyme B production by BTLA+ T cells and was associated with poor outcome in DLBCL and FL, whereas only two studies reported about BTLA and HVEM expression on leukemic cells from CLL." (PMID 33917094, 2021). "Further, BTLA blockade restored, at least in part, the immunosuppression of NK cells, suggesting that targeting BTLA may be a potential therapeutic strategy to be explored in this disease and other hematological malignancies." (PMID 33917094, 2021). "Dysregulation of the BTLA/HVEM axis has been described in a plethora of solid tumors and hematological malignancies." (PMID 37649037, 2023). "BTLA and HVEM expression were next evaluated in other hematological malignancies using publicly available datasets by means of GEPIA2 and GENT2 tools." (PMID 33917094, 2021). "In fact, the potential impact of BTLA dysregulation in the modulation of T cell and NK cell-mediated responses has not yet fully been elucidated in neither hematological malignancies nor solid tumors." (PMID 33917094, 2021).
bacterial infection (4 papers, 2011 to 2021). "This is in contrast to a recent study of systemic bacterial infection using mice deficient in LIGHT, HVEM, or BTLA, which suggested a critical role for BTLA in inhibiting early innate proinflammatory responses." (PMID 21283640, 2011). "Collectively, our data demonstrate that the function of the BTLA-HVEM pathway is not limited to inhibitory signaling in T lymphocytes, and instead, that BTLA can provide crucial, HVEM-dependent signals that promote survival of antigen activated CD8+ T cell during bacterial infection." (PMID 24205057, 2013).
Immune Disorders (4 papers, 2012 to 2024). "A better understanding of how BTLA functions in regulatory T cells will shed light on immune dysfunction in human disease." (PMID 35320716, 2022). "This review aimed to summarize the recent results on the effects of BTLA in regulating immune cell function and to explore its potential role in immune disorders." (PMID 33859648, 2021). "Elevated levels of BTLA on CD4+ T cells will eventually result in CD8+ T-cell immune disorders." (PMID 38418488, 2024). "Therefore, the present work aimed to review the existing knowledge about BTLA in immunity and summarize the diverse functions of BTLA in various immune disorders." (PMID 33859648, 2021).
infectious disease (2 papers, 2012 to 2021). A disorder directly resulting from the presence and activity of a microbial, viral, or parasitic agent in humans. "In infectious disease models, for instance, it has been found that an interruption of BTLA signaling causes the augmentation of the virus-specific cytotoxic lymphocyte (CTL) response, promoting the early clearance of both Listeria bacteria and CMV infection." (PMID 23067542, 2012). "It has been demonstrated that signals from the inhibitory receptor B and T lymphocyte attenuator (BTLA) are involved in regulating the pathogenesis of infectious diseases." (PMID 23067542, 2012).
inflammation (2 papers, 2021). Aberrant reaction of the microcirculation characterized by movement of fluid and leukocytes from the blood into extravascular tissues. "Increasing BTLA expression via either the administration of dexamethasone or the agonistic anti-BTLA antibody 6A6 attenuates LPS-induced acute lung inflammation in mice." (PMID 34163466, 2021). "In patients with severe community-acquired pneumonia and in mice with acute lung inflammation, circulating BTLA+CD4+ lymphocyte proportions markedly increased, whereas agonistic anti-BTLA antibody reduced the activation of the NF-κB pathway and attenuated the inflammatory responses." (PMID 33859648, 2021).
metabolic disorders (2 papers, 2024 to 2025). "GM dysbiosis and inflammation also induce epigenetic alterations in cytokine genes, such as IL-1β, IL-6, TNF-α, NF-kB, BTLA, IL-18R1, TGF-β, P13k/Akt1, Ctnnb1, and Hsp90aa1, as well as DNMTs, HDACs, and DAT1 associated with the development and progression of metabolic disorders and/or NPDs." (PMID 41228440, 2025).
cardiovascular diseases (1 paper, 2024). "Interestingly, while BTLA is strongly expressed on peripheral B cells from patients with cardiovascular diseases, effector B cells within lesions, primarily consisting of NSM and DN B cells, express very low levels of BTLA." (PMID 39768154, 2024).
gastrointestinal disorders (1 paper, 2025). "This functional complexity is supported by clinical findings showing altered expression of HVEM, BTLA, and LIGHT in patients with IBD and related gastrointestinal disorders at different disease stages." (PMID 41030453, 2025). "Clinical and genetic studies further support the role of HVEM as an immune checkpoint, with altered HVEM and BTLA expression profiles identified in patients with IBD and other gastrointestinal disorders." (PMID 41030453, 2025).
hematological cancers (1 paper, 2023). "Despite several studies strongly support the inhibitory and prognostic value of BTLA and HVEM in hematological cancers, there is scarce information to date about the antitumor effects associated to disruption of BTLA/HVEM axis." (PMID 37649037, 2023). "In good agreement, dysregulation of BTLA/HVEM axis has been correlated with prognosis in both solid and hematological cancers." (PMID 37649037, 2023).
respiratory diseases (1 paper, 2021). "BTLA plays an important role in immunoregulation and is involved in the pathogenesis of various respiratory diseases." (PMID 34163466, 2021). "Treatment of respiratory diseases by anti-BTLA antibody must be on the road, more and more application researches will be conducted." (PMID 34163466, 2021). "As a cosignaling molecule, B and T lymphocyte attenuator (BTLA) plays an important role in immunoregulation and is involved in the pathogenesis of various respiratory diseases." (PMID 34163466, 2021). "In recent years, some studies have found that BTLA also has played a positive regulatory effect on immunity system in the occurrence and development of respiratory diseases." (PMID 34163466, 2021). "In this review, we discuss the biological characteristics of BTLA and explore their role in respiratory diseases." (PMID 34163466, 2021). "One reason is that BTLA does not merely serve as an immune suppression role in respiratory system diseases." (PMID 34163466, 2021).
BTLA also shares sentences with these, for which no sentence is quoted: mantle cell lymphoma (3 papers); marginal zone lymphoma (3); acute liver failure (2); adenocarcinoma (2); Burkitt lymphoma (2); colon adenocarcinoma (2); lymphocytic leukemia (2); neoplastic disorders (2); serous ovarian carcinoma (2); Sjögren's syndrome (2); acute leukemia (1); acute respiratory distress syndrome (1); Allergy (1); Alzheimer disease (1); Arthritis (1); Ascites (1); atopic dermatitis (1); autoimmune uveitis (1); Behcet disease (1); colorectal tumor (1); Crohn disease (1); cutaneous melanoma (1); End Stage Liver Disease (1); fulminant viral hepatitis (1); gastric adenocarcinoma (1); Genital ulcers (1); head and neck squamous cell carcinoma (1); heart failure (1); Hepatitis B (1); IgA nephropathy (1).
A further 19 diseases each share a sentence with BTLA in 1 paper.